CD4 (CD4 molecule)
Diseases named in the same sentence as CD4 in open-access papers (continued):
Sharing a sentence is not in itself a finding about the gene and the disease.
Autoimmunity (continued). "Infiltrating CD4+ T cells were found as the source of this IFNγ,3 and the adoptive transfer of IFNγ‐producing T‐cell lines has been demonstrated to promote autoimmune pathologies." (PMID 33135395, 2020). "In this context, neutrophils were shown to produce BAFF and contribute to excess serum BAFF levels, promoting CD4+ T cell and B cell responses in autoimmunity model of lupus-prone mice." (PMID 32849550, 2020). "FOXP3-expressing Tregs, which belong to a suppressive subset of CD4+ T cells, can regulate infection, tumor development, allergy, and autoimmunity." (PMID 32040478, 2020). "Tregs are a small subset of CD4+ T cells that play a pivotal role in the maintenance of immunological tolerance and prevention of autoimmunity." (PMID 32560733, 2020). "More importantly, the downregulation of TonEBP attenuates pathological CD4+ T cell differentiation and autoimmunity." (PMID 32825390, 2020). "The central role of CD4+ T cells across infection, cancer, autoimmunity, and allergy motivates a need to predict which peptide antigens can be presented by MHC-IIs." (PMID 32887877, 2020). "CD4+ T cells also modulate immune homeostasis by suppressing pro-inflammatory immune responses, build immunologic memory, and control autoimmunity." (PMID 33123017, 2020). "Animal models revealed that development of autoimmunity was due to defects in the CD4+CD25+FoxP3+ Treg cell population." (PMID 32256489, 2020). "Tumors use TGF-β in indirect methods of immune evasion: converting CD4+CD25- to CD4+CD25+ Treg cells or inducing the development of a Th17 type response designed to counter autoimmunity and reduce the fraction of activated Th cells." (PMID 35310881, 2020). "In this review, we discuss the inflammatory mediators that activate bystander CD4+ T cells and the potential physiological roles of these cells during infection, autoimmunity, and cancer." (PMID 32859954, 2020). "Recent findings show that both Th17 cells and pTreg cells whose precursor cells are also CD4 T play vital roles in autoimmunity response that can be induced by AR." (PMID 33015714, 2020). "It has been reported that CD4+ T cells and CD8+ T cells play a key antiviral roles by balancing the combat against pathogens and the risk of developing autoimmunity or overwhelming inflammation." (PMID 32746940, 2020). "Regulatory T cells (Tregs) constitute a small proportion of circulating CD4+ T cells that function to maintain homeostasis and prevent autoimmunity." (PMID 33603742, 2020). "Tfh cells are a subset of CD4+ helper T cells that play a crucial role in humoral immunity and protection against pathogens and in the generation of autoimmunity." (PMID 33489909, 2020). "We show that virus-induced type I IFN responses transiently impair the Treg cell compartment, but that this is rapidly replenished by iTreg cells converted from a high-affinity CD4+ T cell pool to prevent inflammatory disorders and overt autoimmunity." (PMID 32251280, 2020). "Treg cells are an immunosuppressive subset of CD4+T cells and play pivotal roles in the prevention of autoimmunity and maintaining immune tolerance." (PMID 32746780, 2020). "As an important component of the immune system, CD4+ T cells play an indispensable role in resisting foreign pathogens and mediate the development of autoimmunity." (PMID 33117376, 2020). "Despite multiple checkpoints and layers of self-governing immune regulation, CD4+Th cell dysfunction can arise, leading to hyper-inflammatory conditions in response to self-antigens (autoimmunity) or exogenous innocuous antigens (such as allergic diseases)." (PMID 32155783, 2020). "Human Th22 cells are tissue-homing CD4+ T cells which have been shown to play an important role in skin and gut disease, autoimmunity and allergy." (PMID 33374787, 2020). "Although we assessed changes in naïve and memory CD4+ T cell subsets using CD27 instead of CCR7 as a marker, none of them revealed an association with presence of secondary autoimmunity." (PMID 32539719, 2020).
Autoimmunity (continued). "As the predominant lymphocyte subset, CD4+T cells play crucial roles in numerous conditions such as infection, autoimmunity, transplantation, and tumor." (PMID 32746780, 2020). "Aberrant regulation of lymphocyte autophagy is involved in autoimmunity, and in previous work, we provided the first evidence of upregulated autophagy in CD4+ T cells infiltrating SS MSG." (PMID 33050949, 2020). "It has recently become apparent that TNF can exert a strong activity on CD4+ Tregs, which are a subset of CD4+ T cells that help to prevent or treat autoimmunity by maintaining self-tolerance, immune homeostasis, and suppression of cytotoxic T cells." (PMID 33066433, 2020). "Tregs, which are distinct from other CD4+ Th cells, play a central role in maintaining peripheral tolerance and protecting against autoimmunity." (PMID 33136553, 2020). "Th17 are CD4+ cells that produce interleukin 17 (IL-17) and are potent inducers of tissue inflammation and autoimmunity." (PMID 33348918, 2020). "Our findings indicate that disorders of homeostasis of PD-1high MP CD4 T cells can result in both inflammatory autoimmunity and impaired adaptive responses against pathogens." (PMID 32709717, 2020). "Future studies will be needed to dissect the roles of these and other non-CD4+ T cell subsets in the pathogenesis of autoimmunity-related CVD." (PMID 33117403, 2020). "A substantial amount of studies has revealed that several PTPs expressed in CD4+ T cells regulate intracellular signaling and are related to autoimmunity, indicating a key regulatory role of these enzymes in immune responses in health and pathology." (PMID 31297117, 2019). "Sf mutant mice lack functional Tregs and develop lethal autoimmunity driven by polyclonally activated CD4+ cells." (PMID 31653839, 2019). "Others have shown that vitamin D suppresses autoimmunity, not only by decreasing the production of IL-17, but also by inhibiting the ability of naïve CD4+ T-cells to commit to the Th17 lineage." (PMID 31752330, 2019). "For instance, RelA is critical for CD4+ Tconv activation since its deletion prevent the development of autoimmunity in Foxp3CreRelaloxmice." (PMID 31749798, 2019). "In immune cells, NR2F6 inhibits CD4+ Th17 T cell responses and autoimmunity arnd suppresses CD4+ and CD8+ T cell-driven anti-tumor immunity." (PMID 31139192, 2019). "Although, the exact pathogenesis of MS remains to be completely elucidated, CD4+T cell-mediated autoimmunity has been accepted as one of the most important aspects of MS pathogenesis." (PMID 31481869, 2019). "In the setting of autoimmunity, the periphery of 3–4-week-old CD25cKO and CD25gKO mice contained a substantial proportion of CD4+ Foxp3+ T cells, albeit diminished in comparison with littermate controls." (PMID 30833563, 2019). "Interferon gamma (IFNG) is a proinflammatory cytokine that is produced by various immune cells, including natural killer and CD4+ T helper 1 (Th1) cells, and plays an central role in the development of autoimmunity." (PMID 31752878, 2019). "Since many CD4+Foxp3GFP− cells from TCRmini and SfTCRmini mice expressed mutual TCRs but only the latter strain developed autoimmunity, we investigated ex vivo autoreactivity of individual TCRs." (PMID 31653839, 2019). "The IL-17+ CD4+ T lymphocytes, also known as Th17 cells, play an essential role in inflammatory responses and autoimmunity." (PMID 30787914, 2019). "Treg induction capacity of naive CD4+ T cells from NOD mice significantly decreased with the onset of IAA+ autoimmunity." (PMID 31836704, 2019). "So far, investigations addressing the role of CD4+ T cells in myocarditis focused on heart-specific autoimmunity." (PMID 31863205, 2019). "Recently, some evidences suggest the development of autoimmunity due to a deficiency in TC-PTP in naïve and follicular helper CD4+ T cells, as well as in B cells." (PMID 31297117, 2019).
Autoimmunity (continued). "Tregs, a subset of CD4+T cells which play a crucial role in the maintenance of immune tolerance and prevention of autoimmunity, are significantly reduced in GBS patients and EAN animals." (PMID 31481869, 2019). "At approximately 1 year of age, CD4-ERα KO mice spontaneously showed mild autoimmunity with increased autoantibody production and CD4+CD44+CXCR5+Bcl-6+ TFH cells in the mesenteric lymph nodes and spleen." (PMID 30988419, 2019). "These manifestations are different from those of Regnase-1 deletion, which results in splenomegaly, autoimmunity, and premature death, which occur upon CD4-specific deletion." (PMID 31126966, 2019). "In this regard, immunogenic DCs produce IL-12 and IL-23 favouring the acquisition of Th1 and Th17 inflammatory phenotypes, respectively, by autoreactive CD4+ T-cells, thus promoting autoimmunity." (PMID 31355296, 2019). "PD-1 signaling is indeed required for the maintenance of functional CD4+CD25+FoxP3+ Tregs to control autoimmunity." (PMID 30650147, 2019). "Here, Tregs aggregate in clusters with activated autoreactive effector CD4 T cells, which they can effectively “govern” given their close proximity, thus suppressing incipient autoimmunity." (PMID 31956323, 2019). "CD4+ regulatory T cells express the transcription factor FoxP3 and are critical in the prevention of excess immunopathology or autoimmunity through multiple mechanisms." (PMID 30429675, 2018). "In lupus-prone mice, targeted delivery of a CaMK4 inhibitor to CD4+ T cells suppresses both autoimmunity and the development of nephritis." (PMID 30333818, 2018). "Other subsets of CD4+ T cells, such as Th1 and Th9 also contribute to the development of neuro-inflammation and autoimmunity." (PMID 29411111, 2018). "Cardiac damage induced by viral myocarditis, myocardial infarction (MI) or cardiotoxic drugs, can be followed by autoimmunity via activation of autoreactive CD4+ T cells." (PMID 30524444, 2018). "Current data have shown that while vitamin D generally suppresses the proinflammatory properties of APC, Th1 and Th17 CD4+ T cells, and B cells, it enhances the anti-inflammatory characteristics of Treg and Th2 cells in many autoimmune conditions." (PMID 30103428, 2018). "Although CD4+Foxp3+ regulatory T cells (Treg) are crucial for prevention of autoimmunity, the therapeutic effect of these cells on lupus nephritis is not satisfactory." (PMID 29441062, 2018). "Naringenin impacts CD4+ T cell differentiation in a manner that would explain its beneficial effect in preventing/mitigating T cell-mediated autoimmunity." (PMID 30327657, 2018). "Here, we analyze what is known about the regulatory circuit of miRNAs and cytokines in CD4+ T lymphocytes, and how this bidirectional system is dysregulated in conditions of pathological inflammation and autoimmunity." (PMID 30622533, 2018). "Similar results were obtained in young TC mice before the production of anti-dsDNA IgG, indicating that CD4+ T cell activation and the expansion of TEM and TFH CD4+ T cells precedes the manifestation of autoimmunity." (PMID 30348969, 2018). "Alternatively, CD4+CD25+FOXP3+ Tregs are classically associated with immunosuppression, attenuation of autoimmunity, and the inhibition of CD4+ proliferation." (PMID 32914058, 2018). "IL-17-expressing T cells (termed Th17) and CD4+CD25+Foxp3+ regulatory T cells (termed Treg) are newly defined CD4+ T cell subsets, which have opposite effects on autoimmunity and inflammation." (PMID 29686529, 2018). "Foxp3+CD4+ regulatory T (Treg) cells are essential for preventing fatal autoimmunity and safeguard immune homeostasis in vivo." (PMID 30560927, 2018). "While rebound Tregs are dysfunctional 32, DT‐resistant Foxp3+ Tregs have been shown to protect against lethal autoimmunity and suffice to control the self‐reactive (SR) CD4+ T cells during chronic mouse hepatitis virus infection." (PMID 28621034, 2017).
Autoimmunity (continued). "We showed that 7α,25-OHC promotes memory CD4+ T cell migration to the target inflammatory organs during autoimmunity." (PMID 28993775, 2017). "Taken together, our results suggest that B7-H4 expressed on DCs plays an important role in negative regulation of autoimmunity in lupus mice through bonding the putative receptor on CD4+ T cells and influencing the regulatory T cells." (PMID 29321778, 2017). "Of the effector T cell subsets, CD4+CD25highFoxp3+ Treg cells are pivotal for maintaining peripheral self-tolerance and controlling autoimmunity by suppressing the activation and expansion of autoreactive T cells and other pathogenic immune cells." (PMID 28830352, 2017). "Here we present a large study of TCR repertoire in autoimmunity (>200 million sequences and 18 million unique clonotypes) performed on ex vivo sorted CD4+ T cell subsets." (PMID 29176645, 2017). "This is particularly true for the CD4+ T cell, which is viewed as the main initiator and driver of autoimmunity in T1D9–11." (PMID 29176645, 2017). "The logical next step is to confirm the possible link between CMV, CD4+CD28null T cells and autoimmunity." (PMID 28386103, 2017). "As a result CD4 T cells become activated, cross the blood brain barrier and induce CNS autoimmunity." (PMID 28686222, 2017). "Regulatory T cells (Tregs; originally known as suppressor T cells) are a subset of CD4+ T cells that modulate immunity, maintain tolerance against self-antigens and prevent autoimmunity." (PMID 28686222, 2017). "CD4+ T cells have been reported to play a central role in the control of autoimmunity, immune homeostasis, and immune responses to pathogens and tumor antigens." (PMID 29267496, 2017). "Naturally occurring CD4+CD25+ regulatory T cells (Tregs) are essential for the active suppression of autoimmunity." (PMID 28270700, 2017). "OX40 signals are the main driver of autoimmunity in Foxp3KO mice, and one potential worry is that blockade of OX40 signals would compromise CD4 immune function, rendering patients susceptible to infection." (PMID 28646041, 2017). "This study further supports the view that central nervous system autoimmunity is mediated by the action of CD4 T cells." (PMID 27925187, 2017). "The distinct in vitro effects of NaCl + LA on naïve CD4+ T cells prompted us to examine their effects in vivo using murine MOG35–55 EAE as a model of Th1/Th17 cell-mediated autoimmunity." (PMID 28899400, 2017). "For instance, differential DNA methylation analysis in CD4+ T cells in lupus patients compared to normal healthy controls identified several genes with known involvement in autoimmunity." (PMID 28213474, 2017). "Since functional Foxp3+CD4+ T cells have immune suppressive activities, they are able to attenuate hyperimmune responses and the inflammatory, allergic, and autoimmune disorders due to these responses." (PMID 27445434, 2016). "Naturally occurring CD4+CD25+ regulatory T cells (Tregs) are essential for the suppression of autoimmunity and can control the immune-mediated pathology during the early phase of sepsis." (PMID 27941849, 2016). "CVID patients with autoimmunity and/or splenomegaly had a reduced frequency of CD4+ CD25hi Tregs, which was more accentuated in those with splenomegaly; additionally, they were associated with CD21low B cell expansion." (PMID 27188997, 2016). "Collectively, these results indicate that CD4+ induced IELs, which have a regulatory function in CNS autoimmunity, are influenced by gut environmental stimuli such as the microbiota and dietary AHR ligands." (PMID 27198196, 2016). "In autoimmunity, aberrant CD4+ T-cell responses are frequently observed, which are accompanied by autoantibody production and the IC formation." (PMID 27313579, 2016). "Antigen-specific IL-10-secreting CD4+ T cells (Tr1) and Foxp3+ regulatory T cells (Tregs), both known to control autoimmunity and induced following JHMV infection, were assessed for their relative in vivo suppressive function of SR T cells." (PMID 27708643, 2016).
Autoimmunity (continued). "Further, mice receiving syngeneic CD4+ T cells in which DNA methylation has been inhibited in vitro, and mice with an inducible T cell DNA methylation defect develop lupus-like autoimmunity." (PMID 28239687, 2016). "CD4+ T regulatory cells (Tregs) comprise a heterogeneous population of cells the regulate immune responses and prevent autoimmunity." (PMID 26866695, 2016). "We previously demonstrated that CD4+ T cell converted DN T cells blocked autoimmunity and prevented diabetic onset in NOD mouse models." (PMID 26911290, 2016). "Consistent with the finding that IL-12 is an important driver of Blimp-1-dependent Tr1 cell differentiation in autoimmunity, we found that Blimp-1 and IL-10 expression by IFNγ-producing CD4+ T cells from L. donovani-infected mice required IL-12." (PMID 26765224, 2016). "Past and recent literature suggests that FcγRIIIa is a crucial player for CD4+ T-cell responses during autoimmunity." (PMID 27313579, 2016). "In human autoimmunity, myelin-specific CD4+ T cells from MS patients provide an example of defective cell death mechanisms." (PMID 25852682, 2015). "The opportunity to retrain memory CD4 T cells subsequent to their generation opens up additional avenues for manipulation, especially in the setting of autoimmunity and allergy." (PMID 26441961, 2015). "Tfh cells, a new separate CD4+ T helper lineage, have attracted close attention for their specialized role in assisting B cells and contributing to autoimmunity." (PMID 25889760, 2015). "This point is of special interest, since the clinical manifestations of B19 infection share some characteristics in common with conditions reported to induce cytotoxic CD4+ T-cell function: chronic infection and autoimmunity." (PMID 26246896, 2015). "IL-27 was shown to be a key regulator of IL-10 and IL-17 production by human CD4+ T cells thus providing a dual regulatory mechanism to control autoimmunity and tissue inflammation." (PMID 25698903, 2015). "It had also been identified as a contributing factor in the development of lymphoproliferative diseases in a murine model of autoimmunity, where raised counts of CD4+ T cells with an activated phenotype were noted." (PMID 25487315, 2015). "A key mechanism used by the immune system to prevent autoimmunity is to precisely regulate the differentiation and activation of CD4+ T-helper cells." (PMID 25964886, 2015). "Recent studies in Batf-3−/− mice also showed a defect in the differentiation of CD4 T helper cells into T helper 17 (Th17) cells essential for supporting inflammatory responses involving pathogens or autoimmunity." (PMID 26793192, 2015). "A greater understanding of these factors has the potential to aid the design of more effective vaccines and to improve regulation of pathologic CD4 T cells, such as in the context of autoimmunity and allergy." (PMID 26441961, 2015). "Recently, it has been suggested that T lymphocytes, especially CD4+ T cells, contribute to the progress of autoimmune and inflammation diseases, including ARDS." (PMID 25887535, 2015). "Whereas Treg cells maintain self-tolerance and control the activation and expansion of autoreactive CD4+ T effector cells through an anti-inflammatory response, Th17 cells, in an exacerbated unregulated proinflammatory response, can promote autoimmunity." (PMID 26568963, 2015). "CD4+ T cells are not only key regulators of immune responses but are also involved in pathological processes such as allergy, chronic inflammation and autoimmunity." (PMID 25884400, 2015). "Some of these factors are extrinsic to T cells and can be manipulated in our attempts to induce protective CD4+ T cell immunity or prevent autoimmunity." (PMID 26322045, 2015). "Whereas Th17 cells can promote autoimmunity due to a proinflammatory response, Treg cells maintain self-tolerance and controls activation and expansion of autoreactive CD4+ T effector cells through an anti-inflammatory response." (PMID 26568963, 2015).